LINC01934 (long independently transcribed non-coding RNA 1934)
Gene: Long non-coding RNA gene on chromosome 2 (181,086,076 to 181,409,321, forward strand). Ensembl gene ENSG00000234663.
Diseases named in the same sentence as LINC01934 in open-access papers:
LINC01934 is named in the same sentence as 2 diseases in open-access papers, as found by Europe PMC text mining. Sharing a sentence is not in itself a finding about the gene and the disease. The quoted sentences say what the papers report.
renal carcinoma (1 paper, 2022). A carcinoma arising from the epithelium of the renal parenchyma or the renal pelvis. "The results showed the relative expression values of LINC01934, LINC00158, and AC007728.2 in renal cancer tissue were substantially greater than in healthy tissue." (PMID 35719925, 2022).
tumor (1 paper, 2022). "These 8 lncRNAs (AL365361.1, LINC01934, AC090152.1, PCED1B-AS1, LINC00426, AC007728.2, AC243829.4, and LINC00158) were found to be positively correlated with immune cells of the tumor microenvironment." (PMID 35719925, 2022).